IGF1 (insulin like growth factor 1)
Diseases named in the same sentence as IGF1 in open-access papers (continued):
Sharing a sentence is not in itself a finding about the gene and the disease.
breast cancer (continued). "NR2F1-AS1 was shown to act as a ceRNA by sponging miR-338-3p, preventing it from downregulating IGF-1; the resulting increase in IGF-1 activated IGF1R in endothelial cells, increasing ERK signaling and breast cancer angiogenesis." (PMID 35597813, 2022). "IGF1, in turn, stimulated GASP1 expression by activating the PI3K/AKT pathway, forming a vicious cycle propelling the malignant progression of breast cancer." (PMID 36042202, 2022). "Furthermore, this link might account for the lack of association between android fat distribution and ER+ breast cancer risk since, in stark contrast to obesity, higher WHRadjBMI was associated with elevated rather than lower circulating IGF-1." (PMID 36558416, 2022). "Here, we demonstrated the IGF-1/IGF-1R signaling axis to induce FASN protein and mRNA expression in breast cancer cells." (PMID 36096767, 2022). "TRIM47 knockdown inhibited the occurrence and development of breast cancer by suppressing the PI3K/Akt pathway, which was reversed by treatment with the PI3K/Akt activator insulin-like growth factor-1 (IGF-1)." (PMID 36249749, 2022). "One such mechanism is the activation of signaling pathways, in particular the insulin-like growth factor 1 (IGF-1) receptor, which is also known to impede trastuzumab-mediated growth inhibition in breast cancer cells." (PMID 35233007, 2022). "They used MCF-7 breast cancer cells which had lost their ERα and showed reduced expression of IGF-signaling and failure to proliferate when stimulated with E2 or IGF-1." (PMID 35784325, 2022). "Our findings support a likely causal role of genetically predicted levels of testosterone, HDL cholesterol, and IGF-1, as well as a novel potential role of ALP in breast cancer aetiology." (PMID 36424572, 2022). "A longer nighttime fast is associated with improved glycemic control, decreased breast cancer biomarkers such as leptin and insulin-like growth factor 1 (IGF-1), and overall reduced breast cancer recurrence." (PMID 35186923, 2022). "For instance, in lung cancer, FOXA1 increases expression of IGF-IR49, whilst in luminal B breast cancer, FOXA1 has been shown to regulate insulin growth factor 1 (IGF1) activity." (PMID 36446866, 2022). "Subsequently, 10 top hub genes were identified and five (IGF1, ADIPOQ, PPARG, LEP, and NR3C1) significantly correlated with worse OS and BCSS on response to trastuzumab in breast cancer patients." (PMID 35317079, 2022). "The cell-surface IGF1 receptor (IGF1R), which mediates the biological actions of both IGF1 and IGF2, is regarded as a central player in breast cancer." (PMID 35432218, 2022). "Many studies have established that IGF-1 and IGF-2 increase proliferation and growth of breast carcinoma cells in vitro, and mouse models reveal that tumor growth in distal tissues is enhanced by signaling through the IGF-1R." (PMID 36556357, 2022). "Lycopene delayed insulin-like growth factor 1 (IGF-1)-induced cell cycle progressionand apoptosis in the MCF-7 breast cancer cell line." (PMID 34822465, 2021). "Several factors of the bone microenvironment, such as the growth factors TGFβ or IGF-1, were shown to play a crucial role in the activation of AKT in bone-metastatic breast cancer cells." (PMID 34064589, 2021). "Previous studies have shown that in breast cancer cell lines, activation of EGF or IGF-1 pathways can sharply lower the expression of PR." (PMID 34022815, 2021). "In breast cancers, IGFBP-3 has the capability to promote tumour growth through either IGF-1-dependent or IGF-1-independent pathways 12,15." (PMID 34512163, 2021). "Similarly, tamoxifen may decrease IGF1 gene expression in breast cancer cells." (PMID 34606580, 2021). "In breast cancer cell lines, IGF-I (insulin-like growth factor 1) expression induces BNIP3 expression through a HIF-1-dependent mechanism." (PMID 33763351, 2021).
breast cancer (continued). "Particularly, in breast cancer, cells IGF1R and CXCR4 directly interact at the cell membrane, and this interaction allows IGF1 to promote cell migration through transactivation of CXCR4." (PMID 33673232, 2021). "In liver-specific IGF-1 gene-deleted (LID) mouse model, incidence of mammary tumors was lower and tumor formation was delayed compared with control mice." (PMID 33429867, 2021). "Breast cancer mitogen insulin-like growth factor 1 (IGF-1) levels increase in AA women after multiple pregnancies and promote breast cancer progression." (PMID 32824813, 2020). "We leveraged the knowledge of IGF1 signaling and biology as a model system to identify a lncRNA, SNHG7, that is important for proliferation and breast cancer biology." (PMID 32444795, 2020). "To further consolidate the role of IGF‐1 in the angiogenetic effects of lncRNA NR2F1‐AS1, we then examined the protein expression of IGF‐1 in transfected breast cancer cells." (PMID 32548873, 2020). "The IGF1 receptor (IGF1R), which mediates the biological actions of IGF1 and IGF2, exhibits potent antiapoptotic and cell-survival activities and is regarded as a key player in breast cancer etiology." (PMID 32391121, 2020). "MCM and hCM greatly increased the expression of IL-6, IL-1β, IL-1α, TNF-α, IGF-1, and MCP-1 compared with control at the mRNA levels in MCF-7 and MDA-MB-231 cells, while the little effect on the VEGF expression in mCM treated-breast cancer cells." (PMID 32201525, 2020). "Several growth factor–related breast cancer genes (EGF, IGF1, IGF1R, IGF2, IGFBP3, IL10, TGFB1, and VEGF), including 26 SNPs, were used as simulation data to evaluate existing algorithms and the proposed HTGA." (PMID 32554381, 2020). "In the present study, chemerin treatment significantly inhibited the viability and invasion of breast cancer cells in the absence or presence of transforming growth factor (TGF)-β and insulin-like growth factor (IGF)-1." (PMID 32325994, 2020). "In our initial study on IGF1R aAb, we isolated immunoglobulins from adult patients with GO and tested their effects on IGF1 signaling and the proliferation of MCF7 breast cancer cells in vitro." (PMID 31940750, 2020). "IGF1 was able to activate the AKT‐PI3K and MAPK pathways and upregulate Cyr61, which induced breast cancer growth and invasion." (PMID 32851683, 2020). "In the breast cancer cohort, the Diff (%) was − 124% for SDF-1β, 52% for IGF1, and 132% for IGFBP7, respectively, confirming that the approach can detect a 10-fold difference in protein levels, described by Diff (%) > 120%." (PMID 33267867, 2020). "Cord blood IGF-1 concentrations have been found to be higher among Caucasian neonates than Chinese neonates and it has been hypothesised that these differences may be responsible, in part, for the differences in breast cancer risks observed between these two populations." (PMID 30737679, 2019). "A similar effect has also been observed in the human breast cancer cell line MCF-7 in vitro, where insulin-like growth factor 1 (IGF-1) induces BNIP3 expression in a HIF-1α dependent-manner." (PMID 31121959, 2019). "FUT8 promotes breast cancer cell invasiveness by remodeling TGF-β receptor core fucosylation and drives the proliferation and invasion of trophoblastic cells via the Insulin-like growth factor 1 (IGF-1)/IGF-1R signaling pathway." (PMID 31022917, 2019). "α9-nAChR synergizes mainly with epidermal growth factor (EGF) receptor, insulin-like growth factor 1 (IGF-1) receptor, vascular endothelial growth factor (VEGF) receptor in lung cancer cells, and estrogen receptor α (ERα) in breast cancer cells." (PMID 31835799, 2019). "On the other hand, prior studies have denoted the importance of circulation IGF1/IGFBP-3 M ratio in almost different malignancies, such as breast cancer." (PMID 31752829, 2019). "Conversely, estrogen influences the IGF-1 pathway by increasing the expression of both IGF-1R and IRS1 in breast cancer cells." (PMID 30692633, 2019).
breast cancer (continued). "Moreover, PRMT1 inhibitors could concomitantly target nongenomic ERα and IGF-1 signaling, two pathways largely implicated in breast cancer development." (PMID 30692633, 2019). "In breast cancer, CG facilitated the E-cadherin-dependent aggregation of mammary carcinoma cells, MCF-7, and it was through insulin-like growth factor-1 signaling." (PMID 31010242, 2019). "The anti-apoptotic and tumorigenic effect of IGF1 is mediated by binding to its cognate receptor, IGF-1R, which is frequently overexpressed in breast cancer." (PMID 30185144, 2018). "Several studies had shown a lower level of insulin-like growth factor (IGF-1) in patients with preeclampsia, while higher IGF-1 is found in patients with breast cancer and women with high mammographic density." (PMID 29361985, 2018). "Emerging evidence suggests that IGF-1 and IGF-1R signaling play a pivotal role in the oncogenic transformation, growth and survival of a variety of cancers, including prostate cancer, breast cancer, colon cancer, and myeloma." (PMID 30213025, 2018). "Further, experimental evidence in breast cancer cell lines suggests that cross-talk between signaling pathways of steroids and growth factors such as EGF or IGF-1 is necessary to induce cell growth and proliferation." (PMID 30400783, 2018). "In breast cancer cells, transcriptional activity of IRS-1 can be increased by steroidal hormones such as estrogen and progesterone respectively in response to IGF-1." (PMID 29787591, 2018). "Our results suggest that the known variants in the genes of the IGF-1 axis play minor roles in the timing of elevation of IGF-1 and IGFBP-3 protein levels during puberty, similar to the role that SNPs in IGF-1 axis genes play in breast cancer." (PMID 30249230, 2018). "We recently reported that, in breast cancer cells, IGF-1R functionally crosstalks with DDR1 and this interaction increases IGF-1R stability and enhances protumorigenic actions of IGF-1." (PMID 28591735, 2017). "Given the important role of IGF-1 system in breast cancer cells and the ensure response of both MCF7 and MDA-MB-231 cells to IGF-1, we treated these cells with IGF-1 for 0, 8, and 24 hours." (PMID 29162853, 2017). "Our current results suggest that long-term DHEA feeding can also protect against liver steatosis by reducing body weight gain and reducing serum IGF-1 and IGFBP-3 in an obese breast cancer model." (PMID 28335515, 2017). "Significantly, we have previously shown that IGF-1, IGF-2 and insulin induce DDR1 upregulation in breast cancer cells by activating the AKT/miR199a-5b pathway." (PMID 28591735, 2017). "This study investigated the effect of N-linked glycosylation on the binding of Herceptin to HER2 protein in breast cancer and on the sensitivity of cancer cells to the chemotherapeutic agent doxorubicin (DXR) and growth factors (EGF and IGF-1)." (PMID 28223691, 2017). "Together, our study implicates phenformin-mediated IGF1/IGF1R regulation as a potential anti-cancer mechanism and supports the development of phenformin and other biguanides as breast cancer therapeutics." (PMID 28947975, 2017). "Next, we used GPER-positive but estrogen receptor (ER)-negative primary CAF cells derived from patient breast tumours and SKBR3 breast cancer cells to investigate the role of GPER in the regulation of VEGF expression and angiogenesis triggered by IGF1." (PMID 29212519, 2017). "To note, phenformin suppressed general IGF1-induced RTK activation and EMT marker expression in BT474 breast cancer cells as well." (PMID 28947975, 2017). "Our results suggest that DHEA feeding can protect against liver steatosis by reducing body weight gain and modulating serum IGF-1 and IGFBP-3 levels in an obese breast cancer rat model." (PMID 28335515, 2017). "Herein, we also show that IGF1 activates the HIF-1α-dependent expression of GPER, required for the regulation of VEGF in CAFs and breast cancer cells." (PMID 29212519, 2017).
breast cancer (continued). "To date, YBX1 has been shown to be phosphorylated only on S102 after insulin growth factor 1 (IGF-1) treatment, an event that fundamentally affects YBX1 function in human breast cancer MCF7 cells." (PMID 26318844, 2015). "This is the first study to evaluate the relationship of tissue expression of IGF1, IGFR1, IGFBP2, and IGFBP3 and survival in US breast cancer patients of Asian, Pacific Islander, and Caucasian ancestry." (PMID 25619494, 2015). "We propose that the identification of the mechanism linking the IGF-1/insulin signal and AGR2 promoter activation is important, because it provides insights into the development of anti-breast cancer drugs." (PMID 25956506, 2015). "A large body of evidence indicates the insulin/insulin-like growth factor (IGF-1, IGF-2) pathway in breast cancer progression." (PMID 25874233, 2015). "For example, IGF-I induces mitogenic and anti-apoptotic responses in ER-positive MCF-7 breast cancer cells; however, in ER-negative MDA-MB-231 cells, IGF-1 only positively affects cell motility." (PMID 25749031, 2015). "This is particularly true for the TN breast cancer cells (estrogen-unresponsive), in which IGF1R is largely expressed and IGF-1 stimulates proliferation and survival, making them responsive in vitro to anti-IGF1R therapies." (PMID 26449867, 2015). "Five genes—CYP19A1, EGFR, ESR2, FOS, and IGF1—were common among all three EDCs–PCB 153, phthalates and BPA, breast cancer, and endometriosis." (PMID 26512648, 2015). "Five genes—CYP19A1, EGFR, ESR2, FOS, and IGF1—were common among all three EDCs–PCBs, phthalates and BPA, 17β-estradiol, breast cancer, and endometriosis." (PMID 26512648, 2015). "Increased levels of insulin-like growth factor 1 (IGF-1) in serum/plasma are seen in prostate cancer and pre menopausal breast cancer." (PMID 25806358, 2015). "Insulin/Insulin like growth factor 1 (IGF-I) and estrogens have potent positive effects on cell proliferation in breast cancer." (PMID 25034939, 2014). "We observed that knockdown of Gi1/2/3 not only clearly reduced the growth rate of breast cancer cells, but also significantly diminished their invasion ability in response to EGF, bFGF, IGF-1 and FBS." (PMID 24521094, 2014). "Since relatively high circulating IGF-1 concentration is associated with increased cancer risk, modulation of IGF-1 levels by soy isoflavone intake may be implemented as a risk reduction mechanism, particularly for breast cancer as reported in our previous studies." (PMID 25285521, 2014). "Our data also suggest that APP is involved in IGF-1/AKT signaling pathways, which are key regulatory pathways for cell growth and survival of breast cancer." (PMID 25491510, 2014). "It is difficult to explain why increased serum IGF-1 level may have a protective effect on the risk of cervical cancer observed, whereas the unfavorable effect of serum IGF-1 is addressed in certain sex hormone-related cancers, such as prostate or breast cancer." (PMID 25333772, 2014). "The PI3K/Akt pathway was assessed given that it is one of the central downstream pathways from IGF-1 and previous studies from our group and others identified a central role of PI3K/Akt in breast cancer outcomes." (PMID 25062088, 2014). "Because Akt and ERK1/2 signaling is required for cell growth and migration in response to growth factors, based on above observations, we reasoned that Giα proteins are involved in growth and invasion of breast cancers in response to EGF, bFGF, IGF-1 and FBS." (PMID 24521094, 2014). "IGF-1 and IGF-2 are strong mitogens in a variety of cancer cell lines, including breast cancer, colon cancer, prostate cancer, and myeloma." (PMID 25424625, 2014). "The critical pathway by which IGF-1 and IGF-2 stimulate breast cancer cell proliferation is the PI3K pathway that leads to increases in AKT activity." (PMID 24171117, 2013).
breast cancer (continued). "Recently, we have demonstrated that the mitogenic factors E2 and insulin-like growth factor-1 (IGF-1) lead to inhibition of Par-4 expression, suggesting that this downregulation contributes to breast cancer cell survival." (PMID 23760770, 2013). "It has in fact been shown in MCF7, MDA-231 and MDA-468 breast cancer cells that treatment with leptin can phosphorylate IGF1R and activate downstream signaling while treatment with IGF1 phosphorylates leptin receptor and activates downstream signaling." (PMID 24260287, 2013). "We found that, like the breast cancer lines, RCC lines varied in their sensitivity to IGF-1 stimulation." (PMID 23548153, 2013). "Klotho is identified as a potential tumor suppressor and an inhibitor of the IGF-1 pathway and activator of the FGF pathway in human breast cancer." (PMID 23516476, 2013). "In breast cancer (MCF-7) and lung cells (NCI-H226), lycopene has been reported to reduce IGF-1 levels and to increase IGFBPs." (PMID 23970935, 2013). "Considered together, these data show that small-molecule inhibitors of MEK1 effectively block the proliferative and antiapoptotic action of IGF-1 and enhance the ability of 4-OHT and MIF to induce an ROS-dependent apoptosis in ER+ MCF-7 breast cancer cells." (PMID 22429491, 2012). "EGR1 is a transcription factor that acts as a tumor suppressor in breast cancer cells, whereas IGFBP1 regulates cell proliferation by binding to and inhibiting IGF1 effects." (PMID 22848683, 2012). "Work with another human breast cancer cell line, MCF-7, has demonstrated that LIV-1 expression is induced by estradiol, IGF-1 and IGF-2, as well as by insulin." (PMID 22852056, 2012). "IGF-1 signaling is a mediator of both PI3K/AKT and MAPK signaling and has been demonstrated to enhance breast cancer tumorigenessis." (PMID 23226206, 2012). "Using this method, we studied the pharmacological profile of IGF1, insulin and insulin analogues on PIP3 production in MCF-7 and MDA-MB231 breast cancer cells." (PMID 22848683, 2012). "Insulin like growth factor-1 (IGF-1) was chosen because it is highly relevant in breast cancer and because measuring serum IGF-1 levels by conventional methods is complicated due to specific IGF-1 serum binding proteins." (PMID 21888628, 2011). "In ER-positive breast cancer cells, IGF-1R and ERα are often coexpressed and respond to the synergistic action of estrogen and IGF-1 signaling, leading to cross-talk between the ER and IGF-1R pathways." (PMID 21595894, 2011). "This study gives further insight into the specific pathways that are required for latent TGF-β activation and highlights the importance of IGF-1 levels and TGF-β activity in cells, particularly breast cancer cells." (PMID 21535875, 2011). "Taken together our data suggest a novel a link between IGF-1 levels, MMP activity, TGF-β signaling, and EMT in breast cancer cells." (PMID 21535875, 2011). "Since activation of this pathway and the subsequent nuclear localization of β-catenin is a hallmark of EMT, we chose to look at the nuclear localization of β-catenin after IGF-1 and latent TGF-β1 treatment of MCF-7 breast cancer cells." (PMID 21535875, 2011). "Our results consistent with recently published paper which demonstrated that klotho can act as a tumor suppressor and a modulator of the IGF-1 and FGF pathways in human breast cancer." (PMID 20642846, 2010). "Intriguingly, a recently published research suggests that klotho serves as a potential tumor suppressor and identify it as an inhibitor of the IGF-1 pathway and activator of the FGF pathway in human breast cancer." (PMID 20642846, 2010). "There is precedence for the role of IGF-1 in this regard via its effects on MMPs, such as MMP-2 and MMP-9 in MCF-7 breast cancer cells and in androgen-independent PC3 prostate cancer cells." (PMID 18598360, 2008).